IL1R1 (interleukin 1 receptor type 1)
Diseases named in the same sentence as IL1R1 in open-access papers (continued):
Sharing a sentence is not in itself a finding about the gene and the disease.
hemarthrosis (1 paper, 2025). Bleeding into the joints. "During the acute phase (day 3), all M1 markers were elevated in response to hemarthrosis (Il6, Il1β, Nos2, Cxcl2 and Il1r1), whereby Il6 and Nos2 were suppressed to baseline levels by rhFVIII and mFcFVIII alike, without effects on Il1β, Cxcl2 and Il1r1." (PMID 40388523, 2025).
hepatocellular carcinoma (1 paper, 2017). A malignant tumor that arises from hepatocytes. "Interference with IL-1α signaling or ablation of IL-1R1 inhibited hepatocellular carcinoma (HCC) development." (PMID 28152513, 2017).
hyperuricemia (1 paper, 2025). An abnormally high level of uric acid. "Loci contributing most strongly to the non-hyperuricemia causal effect included three genes: IL1R1, IL1RN, and SLC30A5." (PMID 40385401, 2025).
IgA nephropathy (1 paper, 2017). "In this study, we study the association between genetic variants of IL-1R1 and IL-1R2 and IgA nephropathy risk in the Chinese Han population." (PMID 28881593, 2017).
ileitis (1 paper, 2019). "Thus, alternative pathways may be considered such as the activation of the NLPR3 inflammasome complex, which is supported by reduced T.gondii induced ileitis in IL-1R1 deficient mice." (PMID 31057534, 2019).
ileus (1 paper, 2024). Decrease in peristalsis in the absence of a mechanical bowel obstruction. "Previous studies also showed that the activation of IL-1 receptor type 1 (IL1R1) specifically on enteric glia protects mice from development of postoperative ileus after intestinal manipulation." (PMID 38957473, 2024). "Activation of IL-1R1 in EGCs typically results in the release of inflammatory mediators in postoperative ileus such as IL-6 and CCL2 that activates immune cells." (PMID 38957473, 2024).
infarction (1 paper, 2022). A localised pathological necrosis of tissue resulting from obstruction of the blood supply usually by a thrombus, an embolus, or vascular torsion. "Thus, it is not surprising that fibroblast-specific disruption of the type 1 IL-1 receptor (IL1R1), the only signaling receptor for IL-1, attenuated collagen deposition and reduced fibrosis in an infarction model." (PMID 35563692, 2022). "Fibroblast-specific IL1-R1 drives adverse cardiac remodeling and promotes ventricular wall thinning and collagen deposition in a model of non-reperfused infarction." (PMID 35563692, 2022).
ischemic cardiomyopathy (1 paper, 2011). Ischemic cardiomyopathy is a cardiomyopathy in which a weakness in the muscle of the heart due to inadequate oxygen delivery to the myocardium with coronary artery disease being the most common cause. "In this mouse model of severe ischemic cardiomyopathy, the lack of signaling through the IL-1R1 signaling post-AMI is associated with a more favorable remodeling." (PMID 22140485, 2011).
ischemic disease (1 paper, 2019). Lack of blood supply to an area of the body, resulting in impairment of tissue oxygenation. "IL1R1 is a IL1 receptor antagonist which blocks the actions of IL1 and has been identified as a therapeutic candidate in ischemic diseases." (PMID 31711504, 2019).
keloid (1 paper, 2025). An irregularly shaped, elevated mark on the skin caused by deposits of excessive amounts of collagen during wound healing. "Mechanistically, fibromodulin accelerates and prolongs the formation of the interleukin 1β-interleukin 1 receptor type 1-interleukin 1 receptor accessory protein ternary complex to increase the apoptosis of myofibroblasts and keloid- and hypertrophic scar-derived cells." (PMID 40221432, 2025).
kidney cancer (1 paper, 2023). Primary or metastatic malignant neoplasm involving the kidney. "PIK3CA, IL1R1, HSP90AA1, and ATG5 were significantly lower expressed in tumor tissues (p < 0.05), which were further confirmed by the protein expression profile in kidney cancer downloaded from HPA database." (PMID 36932108, 2023).
Lipedema (1 paper, 2022). Disorder of adipose tissue characterized by symmetric and bilateral enlargement of the lower extremities due to abnormal deposition of subcutaneous fat often in obese women. "Importantly, the expression of IL1b, the IL1R1 and other IL1b related genes were downregulated in the RNA sequencing in our lipedema samples." (PMID 36605202, 2022).
Lysosomal disease (1 paper, 2023). "Notably, within the context of a lysosomal disease, overexpression of IL-1Ra or abrogation of Il-1R1 in a mouse model of MPSIIIA halted the development of pathological hallmarks, including a striking reduction in reactive astrocytes, which is evidence of interleukin-1 being a driver of astrogliosis." (PMID 36519759, 2023).
metaplastic breast carcinoma (1 paper, 2024). A group of invasive breast carcinomas characterized by the presence of an adenocarcinomatous component which is admixed with a dominant component that is composed of squamous cells, spindle cells, or mesenchymal cells. "While invasive mixed mucinous carcinoma (the most abundant sub-type) was predominantly seen in IL1R1 low samples, metaplastic breast cancer was only found within the IL1R1 high samples." (PMID 39728924, 2024).
migraine (1 paper, 2022). "Blocking these pathways using immunologic agents such as CGRP antibody, anti-CGRP receptor antibody, and interleukin-1 beta (IL-1β)/interleukin 1 receptor type 1 (IL-1R1) axis-related agents may be promising as potential prophylactic migraine treatments." (PMID 36247795, 2022).
myelofibrosis (1 paper, 2022). A partial or complete replacement of the bone marrow stroma by fibrous tissue. "To determine the contribution of IL-1 signaling in the pathogenesis of MPN/MF, we examined the effects of genetic deletion of IL-1R1 in a homozygous Jak2V617F (Jak2VF/VF) knock-in mouse model of myelofibrosis." (PMID 36100596, 2022). "Collectively, these results suggest that IL-1 signaling plays a pathogenic role in MPN disease progression, and targeting of IL-1R1 could be a useful strategy for the treatment of myelofibrosis." (PMID 36100596, 2022). "Results from our studies suggest that therapies targeting IL-1R1 could be useful for the treatment of myelofibrosis." (PMID 36100596, 2022).
myeloid malignancies (1 paper, 2022). "To determine the clinical relevance of IL-1R1 expression in patients with myeloid malignancies, we examined two publically-available datasets for IL-1R1 expression levels and correlated these levels with survival." (PMID 35962058, 2022).
myoma (1 paper, 2012). "The myoma model also enabled us to show high expressions of cytokines, such as IL-1a, IL-1R1, IL-8, and NF-κB, which are all known to have reciprocal interactions." (PMID 23342263, 2012).
neonatal-onset multisystem inflammatory disease (1 paper, 2016). "Given that rIL-RA was approved for the treatment of neonatal-onset multisystem inflammatory disease (NOMID) in 2012, rIL-RA is an ideal candidate drug targeting IL-1R1 to prevent FS generation as well as subsequent epileptogenesis, and translational studies in humans may be feasible." (PMID 26902320, 2016).
nephritis (1 paper, 2020). Inflammation of renal tissue. "Indeed, IL-1R1– or IL-1β–deficient mice are protected from anti-GBM IgG-mediated nephritis." (PMID 32541026, 2020).
oral cancer (1 paper, 2021). "IL-1R1 promotes oral cancer growth and metastasis by upregulating CXCR4 (a chemokine receptor involved in tumor progression, angiogenesis and metastasis) after IL-1β stimulation, and IL-1R1 inhibition with recombinant IL-1RA has shown to reverse these effects." (PMID 35048046, 2021).
osteoporosis (1 paper, 2025). A condition of reduced bone mass, with decreased cortical thickness and a decrease in the number and size of the trabeculae of cancellous bone (but normal chemical composition), resulting in increased fracture incidence. "Genetic factors associated with osteoporosis susceptibility in the Chinese Han population have been identified, including rs10490571, rs956730, and rs3917225 in IL-1R1 and rs17042888 in IL-1RN." (PMID 40153574, 2025).
polyp (1 paper, 2014). A usually exophytic mass attached to the underlying tissue by a broad base or a thin stalk. "Significant decreases in IL-1R1 gene were also found when polyp (p < 0.0001) and scar (p < 0.05) were treated with LPS in comparison to controls." (PMID 25606025, 2014). "Normal T21 and T59 VFF expressed significantly higher levels of IL-1R1 after LPS stimulation in comparison to similar conditions with scar (p < 0.01) and polyp VFF (p < 0.0001)." (PMID 25606025, 2014).
preeclampsia (1 paper, 2016). Preeclampsia is a hypertensive disorder of pregnancy that is characterized by new-onset hypertension with proteinuria presenting after 20 weeks of gestation, and depending on mild or severe forms may initially present with severe headache, visual disturbances, and hyperreflexia. "Other molecules of the IL-1 family (IL-1α, IL-18, IL-1R1, IL-1RA, IL-1RAcP, and ST2L) and molecules associated with inflammasomes (NLRP-1, NLRP-3, NLRC-4, caspase I, and ASC) have been reported to be active in early pregnancy, parturition, preterm labor, preeclampsia, and infection during pregnancy." (PMID 27713746, 2016).
pterygium (1 paper, 2023). A wedge-shaped fibrovascular lesion arising from the bulbar conjunctiva and extending to the cornea. "Several DEGs in pterygium and pSS tissues were identified from the datasets, and five hub genes (IL1R1, ICAM1, IRAK1, S100A9, and S100A8) were finally screened out." (PMID 36768371, 2023). "Compared with the healthy control conjunctiva, the expression of five hub genes (IL1R1, ICAM1, IRAK1, S100A9, and S100A8) in pterygium or pSS samples was statistically significant (p < 0.05)." (PMID 36768371, 2023). "We identified a shared gene signature (IL1R1, ICAM1, IRAK1, S100A9, and S100A8) between pterygium presence and pSS." (PMID 36768371, 2023).
pulmonary alveolar proteinosis (1 paper, 2017). A rare lung disorder characterized by the filling of the pulmonary alveoli with proteinaceous material which stains positive with periodic acid-Schiff stain. "One of the other long term responses to MWCNTs in IL-1R1 KO mice was the development of pulmonary alveolar proteinosis." (PMID 28903780, 2017).
pulpitis (1 paper, 2025). Inflammation of the dental pulp. "Furthermore, the inflammatory alteration of IL1R1 blockage was estimated in vivo using the pulpitis model in OC-Cre; Omdfl/fl mice." (PMID 40414936, 2025).
retinopathy of prematurity (1 paper, 2023). A bilateral retinopathy characterized by neovascularization, scarring, retinal detachment, and eventually blindness. "The preclinical peptide rytvela, which has been researched in the retinopathy of prematurity, also blocks the activation IL-1R1 but does so via an allosteric binding site." (PMID 36769133, 2023).
shigellosis (1 paper, 2023). Shigellosis is a bacterial infection leading to dysentery and is caused by Shigella, which are small, ubiquitous Gram-negative bacteria belonging to the enterobacteria family. "To better address the role of IL-1 in shigellosis, we crossed B6.Nlrc4–/– mice to B6.Il1r1–/– mice to generate B6.Nlrc4–/–Il1r1–/– double-deficient mice that are susceptible to Shigella infection but fail to respond to IL-1." (PMID 36645406, 2023).
Sleep disturbance (1 paper, 2016). An abnormal pattern in the quality, quantity, or characteristics of sleep. "This study investigated the roles of IL-1R1 in the thresholds of kindling-induced epileptogenesis and in the kindling-induced sleep disturbances." (PMID 27875989, 2016).
smallpox (1 paper, 2010). A condition that is caused by infection with Variola, and that is characterized by small, raised bumps. "Haplotypes in IL1R1 have been correlated with fever after smallpox vaccination." (PMID 20806065, 2010).
squamous cell carcinoma (1 paper, 2022). A carcinoma arising from squamous epithelial cells. "We also tried to recapitulate the IL1R1+ Treg phenotype in a humanized mouse model of squamous cell carcinoma." (PMID 35545675, 2022).
sweet syndrome (1 paper, 2023). "Clinical remission of refractory Sweet syndrome with anti–IL-1R1 antagonist." (PMID 36355435, 2023).
T-cell lymphoma (1 paper, 2012). "A previous study had determined the mRNA expression profile of EBV-infected nasal NK/T-cell lymphoma lines and found, among others, the IL1A, BCL6, CD44 and c-FOS genes to be induced and the interleukin 1 receptor 1 (IL1R1) gene to be repressed compared to normal lymphocytes." (PMID 22870299, 2012).
Thrombocytopenia (1 paper, 2023). A reduction in the number of circulating thrombocytes. "To more directly investigate the role of IL-1 signaling in CBM-PV cells in the activation of Vwf+ HSCs in response to thrombocytopenia, we induced platelet depletion in mice with conditional deletion of Il1r1 specifically in Lepr+ PV cells." (PMID 37770432, 2023). "Therefore, to investigate if IL-1 may directly mediate the activation of HSCs post anti-GPIbα-induced thrombocytopenia we induced platelet depletion in Il1r1FL/FLVav-iCreTg/+ mice which targets deletion of Il1r1 to all hematopoietic cells, including HSCs." (PMID 37770432, 2023). "The reduction in cell cycle activation was comparable to the one observed in germ-line deleted Il1r1–/– mice, supporting that Lepr+ CBM-PV cells are the main cells involved in IL-1R-dependent activation of Vwf+ HSCs in response to anti-GPIbα-induced thrombocytopenia." (PMID 37770432, 2023).
thyroid cancer (1 paper, 2023). "They found that rs3917225 in IL1R1 as well as rs2072472 and rs11674595 in IL1R2 were linked to susceptibility to thyroid cancer." (PMID 37189693, 2023).
tongue cancer (1 paper, 2015). A malignant neoplasm affecting the tongue. "Sections from 40 of 41 tongue carcinoma tissues stained positively for IL-1R1 protein by immunohistochemistry." (PMID 26176534, 2015). "Eight of 9 poorly differentiated tongue carcinomas (grade III), all 11 moderately differentiated tongue carcinomas (grade II), and all 21 well differentiated tongue carcinomas (grade I), were IL-1R1 positive." (PMID 26176534, 2015).
tongue squamous cell carcinoma (1 paper, 2015). A squamous cell carcinoma that arises from the tongue. "We first detected IL-1R1 protein expression in biopsy specimens of human tongue squamous cell carcinomas." (PMID 26176534, 2015). "When we observed the staining patterns of IL-1R1, we found that tongue squamous cell carcinomas were positive in both the cytoplasm and nucleus." (PMID 26176534, 2015). "Here, we report that IL-1 receptor 1 (IL-1R1) was expressed in 40 of 41 human tongue squamous cell carcinomas (TSCC)." (PMID 26176534, 2015).
triple-negative breast carcinoma (1 paper, 2024). An invasive breast carcinoma which is negative for expression of estrogen receptor (ER), progesterone receptor (PR), and human epidermal growth factor receptor 2 (HER2). "IL1R1 expression in Triple-Negative Breast cancer (TNBC) samples is sensitive to inter-tumoral variation in telomere length." (PMID 39728924, 2024). "Further, IL1R1 expression was telomere-sensitive in triple-negative breast cancer (TNBC) clinical samples." (PMID 39728924, 2024).
tularemia (1 paper, 2015). Tularemia is an infection caused by the bacterium Francisella tularensis. "Thus, different mechanisms determine the increased susceptibility of Il-1r1-/- and Il-18-/- mice to tularemia." (PMID 25768794, 2015).
Ventriculomegaly (1 paper, 2022). An increase in size of the ventricular system of the brain. "Specifically, IL1R1 displayed a log2 fold change (FC) of +0.56 in relation to echolucency and a log2 FC of +0.41 in relation to ventriculomegaly." (PMID 36389237, 2022).
VEXAS syndrome (1 paper, 2025). An adult-onset inflammatory disease that affects only males and is caused by somatic, not germline, mutations. "Furthermore, anakinra, an inhibitor of IL-1/IL-1R1 signaling, and ruxolitinib, an inhibitor of JAK2 signaling, have been reported to treat VEXAS syndrome." (PMID 40906528, 2025).
tumor (224 papers, 2009 to 2026). "CALR is expressed in nearly all cells in the TME, IL1R1 is mainly expressed in tumor-associated fibroblasts and endothelial cells, and the expression levels of IFNG and IFNB1 are minimal, primarily by T lymphocytes." (PMID 40928500, 2025). "Cyclic immunofluorescence was used to stain for protein tags that distinguished IL-1R1-proficient tumor cells from -deficient ones, based on the gRNA they received." (PMID 39236155, 2024). "Telomere length sensitive IL1R1 expression modulates tumour associated macrophage (TAM) infiltration in TNBC." (PMID 39728924, 2024). "In brief, tumor cells either proficient or deficient in IL-1R1 were generated using CRISPR-Cas9 genomics, mixed in equivalent ratios, and injected intravenously into mice." (PMID 39236155, 2024). "RNAseq data for myeloid cell types collected at the onset of CRS revealed that IL-1R1 was up-regulated in tumor-associated myeloid cells, while only IL-1R2 was detected in spleen myeloid cells." (PMID 36100873, 2022). "The importance of IL-1 in MDSC accumulation came from a study showing that tumor bearing IL-1R1-deficient mice presented decreased tumor growth and fewer MDSCs." (PMID 32635472, 2020). "Overexpression of IL-1R1 was positively correlated with the loss of tumor encapsulation and with microvascular invasion and higher TNM stage." (PMID 32206125, 2020). "Additionally, in BLCA single-cell sequencing, we found IL1R1 is abundantly expressed in cancer-associated fibroblasts, linked to tumor promotion and immunosuppression." (PMID 40928500, 2025). "To determine whether there might be a difference in growth fitness between IL-1R1-proficient and -deficient tumor cells, we also evaluated the simultaneous growth of IL-1R1-proficient and deficient tumors in the context of a shared TME." (PMID 39236155, 2024). "Recent studies have implicated IL1R1-related signalling in M2 TAM infiltration in tumours." (PMID 39728924, 2024). "Furthermore, it has recently been demonstrated that IL-1R1 deficit in Neutrophils promotes bacterial invasion and tumor aggressiveness, while IL-1R1 deficiency in epithelial cells decreases tumorigenesis in an APC model." (PMID 37894904, 2023). "IL1R1 was shown to be linked with brain edema and tumor progression in mice." (PMID 35806337, 2022). "This privileged IL-1β-IL1R1 link between macrophages and IL1R1+ iCAFs led us to investigate whether the IL-1β signaling triggered in CAFs could also push tumor-associated macrophages (TAMs) to a tumor-promoting (i.e. an M2-like) phenotype." (PMID 37460545, 2023). "Signaling pathways downstream of IL-1R1 activation might have an important role in cancer-induced behavioral changes, given that cortical and hippocampal IL-1β increases are associated with behavioral outcomes in several other tumor rodent models." (PMID 31019214, 2019). "Next, we examined the impact of IL-1R1 blockade on the tumor microenvironment by comparing the bulk transcriptomes of PDAC tumors." (PMID 40060615, 2025). "IL-1R1’s role in cancer is complex and context-dependent, but it is increasingly recognized as a key driver of tumor progression, metastasis, and immunosuppression." (PMID 41415279, 2025). "Some iCAFs showed high expression of IL1R1 and addition of an IL-1-inhbiting antibody effectively reduced tumour spheroid growth." (PMID 39780187, 2025). "To further confirm the importance of these cytokines in mediating tumor cell susceptibility to macrophage-induced phagocytosis, we knocked out either TNF-α receptor (Tnfrsf1 KO) or IL-1 receptor (Il1r1 KO)." (PMID 41243973, 2025). "IL-1R1 blockade monotherapy downregulated innate and adaptive immune response and exacerbated tumor growth." (PMID 40060615, 2025). "Cell–cell interactions, drug‐target expression analyses in malignant cells after radiation, and multiplex immunofluorescence of tumor tissue identified interleukin‐1 receptor type I (IL1R1) as a potential therapeutic target." (PMID 39903771, 2025).